ENSG00000275180 (novel transcript)
Gene: Long non-coding RNA gene on chromosome 12 (62,603,193 to 62,605,503, forward strand). Ensembl gene ENSG00000275180.
Gene Ontology:
Biological process: miRNA-mediated post-transcriptional gene silencing
Cellular component: RISC complex